CREB3 (cAMP responsive element binding protein 3)
Description:
Endoplasmic reticulum (ER)-bound sequence-specific transcription factor that directly binds DNA and activates transcription. Plays a role in the unfolded protein response (UPR), promoting cell survival versus ER stress-induced apoptotic cell death. Also involved in cell proliferation, migration and differentiation, tumor suppression and inflammatory gene expression. Acts as a positive regulator of LKN-1/CCL15-induced chemotaxis signaling of leukocyte cell migration. Associates with chromatin to the HERPUD1 promoter. Also induces transcriptional activation of chemokine receptors. (Microbial infection) Plays a role in human immunodeficiency virus type 1 (HIV-1) virus protein expression. [Isoform 1]: (Microbial infection) May play a role as a cellular tumor suppressor that is targeted by the hepatitis C virus (HCV) core protein. [Isoform 1]: (Microbial infection) Plays a role in herpes simplex virus-1 (HSV-1) latent infection and reactivation from latency. Represses the VP16-mediated transactivation of immediate early genes of the HSV-1 virus by sequestering host cell factor-1 HCFC1 in the ER membrane of sensory neurons, thereby preventing the initiation of the replicative cascade leading to latent infection. [Isoform 2]: Functions as a negative transcriptional regulator in ligand-induced transcriptional activation of the glucocorticoid receptor NR3C1 by recruiting and activating histone deacetylases (HDAC1, HDAC2 and HDAC6). Also decreases the acetylation level of histone H4. Does not promote the chemotactic activity of leukocyte cells. [Processed cyclic AMP-responsive element-binding protein 3]: This is the transcriptionally active form that translocates to the nucleus and activates unfolded protein response (UPR) target genes during endoplasmic reticulum (ER) stress response. Binds the cAMP response element (CRE) (consensus: 5'-GTGACGT[AG][AG]-3') and C/EBP sequences present in many promoters to activate transcription of the genes. Binds to the unfolded protein response element (UPRE) consensus sequences sites. Binds DNA to the 5'-CCAC[GA]-3'half of ERSE II (5'-ATTGG-N-CCACG-3'). [Processed cyclic AMP-responsive element-binding protein 3]: (Microbial infection) Activates transcription of genes required for reactivation of the latent HSV-1 virus. Its transcriptional activity is inhibited by CREBZF in a HCFC1-dependent manner, by the viral transactivator protein VP16. Binds DNA to the cAMP response element (CRE) (consensus: 5'-GTGACGT[AG][AG]-3') and C/EBP sequences present in many viral promoters. [Processed cyclic AMP-responsive element-binding protein 3]: (Microbial infection) Its transcriptional activity is inhibited by CREBZF in a HCFC1-dependent manner, by the viral transactivator HCV core protein.
Synonyms: LZIP; Luman; sLZIP
Tractability: Antibody: UniProt predicts a signal peptide or a membrane-spanning region. PROTAC: ubiquitination databases record sites on it.
Gene: Protein-coding gene on chromosome 9 (35,732,296 to 35,738,886, forward strand). Ensembl gene ENSG00000107175.
Subcellular location: Endoplasmic reticulum membrane (Isoform 1); Golgi apparatus; Cytoplasm (Isoform 1); Nucleus (Isoform 2); Cytoplasm; Nucleus (Processed cyclic AMP-responsive element-binding protein 3)
Subcellular location (Human Protein Atlas): Cytosol; Basal body; Centrosome; Plasma membrane; Primary cilium; Primary cilium tip; Primary cilium transition zone; Vesicles
Pathways (Reactome):
Cellular responses to stimuli: CREB3 factors activate genes
Gene Ontology:
Molecular function: DNA-binding transcription activator activity, RNA polymerase II-specific; DNA-binding transcription factor activity, RNA polymerase II-specific; identical protein binding; protein binding; RNA polymerase II cis-regulatory region sequence-specific DNA binding; sequence-specific double-stranded DNA binding; transcription coregulator binding; DNA-binding transcription factor activity
Biological process: endoplasmic reticulum unfolded protein response; negative regulation of endoplasmic reticulum stress-induced intrinsic apoptotic signaling pathway; positive regulation of monocyte chemotaxis; positive regulation of transcription by RNA polymerase II; integrated stress response signaling; regulation of transcription by RNA polymerase II; regulation of DNA-templated transcription
Cellular component: cytoplasm; cytosol; endoplasmic reticulum; endoplasmic reticulum membrane; Golgi apparatus; nucleus; RNA polymerase II transcription regulator complex; chromatin; Golgi membrane; nucleoplasm
Genetic constraint (gnomAD): Loss-of-function variants: 31 observed, 36.53 expected, observed/expected ratio (o/e) 0.85, 90% interval 0.64 to 1.14. The upper end of that interval is the gene's LOEUF score, 1.14, which puts it in group 5 of 6, group 1 being the genes least tolerant of losing a copy. Missense variants: 439 observed, 460.41 expected, observed/expected ratio (o/e) 0.95, 90% interval 0.88 to 1.03. Synonymous variants: 183 observed, 183.69 expected, observed/expected ratio (o/e) 1, 90% interval 0.88 to 1.13.
Homologues: Orthologues: chimpanzee CREB3 (99% identical), macaque CREB3 (95% identical), guinea pig CREB3 (74% identical), dog CREB3 (73% identical), pig CREB3 (72% identical), rabbit CREB3 (70% identical), mouse Creb3 (67% identical), rat Creb3 (66% identical), tropical clawed frog creb3 (38% identical), zebrafish creb3l3l (34% identical), Caenorhabditis elegans crh-2 (20% identical), Drosophila melanogaster CrebA (18% identical), and 4 more. Paralogues in human: CREB3L3 (32% identical), CREB3L4 (29% identical), CREB3L1 (27% identical), CREB3L2 (24% identical), ATF6B (22% identical), ATF6 (19% identical), CREB1 (12% identical), ATF1 (12% identical), CREM (11% identical).
Diseases named in the same sentence as CREB3 in open-access papers:
CREB3 is named in the same sentence as 59 diseases in open-access papers, as found by Europe PMC text mining. Sharing a sentence is not in itself a finding about the gene and the disease. The quoted sentences say what the papers report.
osteosarcoma (15 papers, 2019 to 2024). A usually aggressive malignant bone-forming mesenchymal neoplasm, predominantly affecting adolescents and young adults. "In osteosarcoma, downregulation of CREB3, which is targeted by miR‐203a‐3p, resulted in decreased proliferation and migration of tumour cells, while promoting apoptosis." (PMID 38894657, 2024). "Molecularly, CREB3 can bind directly to the c-Jun promoter and regulate the transcriptional activity of c-Jun in osteosarcoma." (PMID 37197432, 2023). "MMP9 and Bcl-2 can be regulated by c-Jun and participate in CREB3-c-Jun modulated osteosarcoma progression." (PMID 37197432, 2023). "Adding to this intricate dynamic is CREB3, a member of the leucine zipper transcription factor lineage, which can intimately bind the c-Jun promoter, thereby steering osteosarcoma evolution through genes like MMP9 and Bcl-2." (PMID 38140058, 2023). "This group concluded that circTADA2A targets an oncogene, CREB3 to promote osteosarcoma progression and metastasis via sponging to miR-203a-3p and emphasized circTADA2A-miR-203a-3p-CREB3 axis as a potent osteosarcoma-targeted therapy." (PMID 35755302, 2022). "In patients with osteosarcoma, circTada2a was reported to promote the development of osteosarcoma and increase tumor malignant behavior through miR-203a-3p/CREB3 axis, which was expected to be a new therapeutic target for osteosarcoma." (PMID 35154330, 2022). "Circular RNA circTADA2A enhances metastasis and progression of osteosarcoma by targeting miR-203a-3p to enhance CREB3." (PMID 34774083, 2021). "Circular RNA circTADA2A promotes osteosarcoma cell metastasis and proliferation by sponging miR-203a-3p and modulating CREB3 expression." (PMID 34675978, 2021). "In another example, circTADA2A promotes osteosarcoma progression and metastasis, and regulates the CREB3 level by sponging miR-203a-3p." (PMID 32381016, 2020). "Likewise, circTADA2A sponges miR-203a-3p, thus disinhibiting cyclic adenosine monophosphate responsive element binding protein 3 (CREB3) and increasing the malignant behavior of osteosarcoma." (PMID 34326275, 2021). "Moreover, they noted that circTADA2A sponged miR‐203a‐3p expression and enhanced CREB3 expression, which was found as one driver gene of osteosarcoma." (PMID 33103338, 2021).
breast carcinoma (12 papers, 2017 to 2025). "Additionally, CREB3 expression has been linked to breast cancer." (PMID 31334233, 2019). "This unique genetic footprint, orchestrated by CREB3, is tethered to enhance metastatic capabilities in breast cancer cells." (PMID 37762375, 2023). "The quest to understand gene expression footprints steered by CREB3-mediated ER-Golgi trafficking unveils repercussions on the metastatic journey of breast cancer." (PMID 37762375, 2023). "A slew of experimental methodologies was deployed in this research, which strove to pinpoint the direct nexus between CREB3-driven trafficking and the invasiveness inherent to breast cancer cells." (PMID 37762375, 2023). "On the other hand, CREB3 is an endoplasmic reticulum stress-related protein, which is reported to promote the malignant progression of breast cancer and glioblastoma (GBM)." (PMID 36358691, 2022). "The CREB3 marker was identified as an oncogene that plays an important role in tumor metastasis in various cancers; including prostate cancer, breast cancer, and osteosarcoma." (PMID 33785763, 2021). "HDAC3 represses CREB3 mediated transcription and migration of breast cancer cells that are metastatic." (PMID 33167967, 2020). "HDAC3 selectively represses CREB3-mediated transcription and migration of metastatic breast cancer cells." (PMID 32571203, 2020). "In both MCF-7 and MD-MB-231 breast cancer cell lines, CREB3 binds specifically to Histone Deacetylase 3 (HDAC3)." (PMID 31334233, 2019). "In breast cancer, CREB3 was identified as a transcriptional regulator of enhanced ADP ribosylation factor 4, COPI coat complex subunit beta 1, and USO1 vesicle transport factor, leading to promotion of endoplasmic reticulum (ER)‐Golgi trafficking and acceleration of tumor cells metastasis." (PMID 38952575, 2024). "Moreover, the CREB3-directed trafficking signature has been painted as a harbinger of grim clinical outcomes in breast cancer patients." (PMID 37762375, 2023). "In addition, CREB3 can accelerate breast cancer metastasis by enhancing the transcriptional activation of ER-Golgi trafficking genes." (PMID 30940151, 2019). "Moreover, in ERα‐positive breast cancer, CREB3 could interact with ERα and suppress its binding to promoter of downstream genes in nucleus, resulting in declined growth of breast cancer." (PMID 38952575, 2024). "However, in estrogen receptor α (ERα)‐positive breast cancer, CREB3 could bind to ERα and inhibit proliferation of breast cancer cell." (PMID 38952575, 2024). "CREB3 has been identified as an HDAC3-interacting protein that enhances NF-κB activation and promotes the migration of breast cancer cells." (PMID 38161382, 2023).
glioblastoma (6 papers, 2016 to 2024). The most malignant astrocytic tumor (WHO grade IV). "Additionally, lower levels of CREB3 were associated with higher relapse-free and overall survival rates in patients with glioblastoma." (PMID 31612863, 2019). "In the case of glioblastoma, heightened expression of CREB3 has been demonstrated to bolster cell proliferation and invasiveness in in vitro studies." (PMID 38894657, 2024). "CREBRF also serves as a tumor suppressor gene in glioblastoma as it negatively regulates cyclic-AMP-response element binding 3 (CREB3) to prevent protective autophagy in hypoxic conditions, leading to increased apoptosis." (PMID 35456993, 2022). "In this study, we explored the mechanisms by which CREB3 regulates the proliferation, invasion and apoptosis of glioblastoma." (PMID 31612863, 2019). "The area under the curve for CREB3 was 0.7845 in discriminating between glioblastoma and adjacent normal tissues, indicating that the experimental results were reliable." (PMID 31612863, 2019). "The CREB3 pathway has been reported to promote the malignant progression of glioblastoma; however, the mechanism remains elusive." (PMID 31612863, 2019). "Among the DEGs, CREB3 was obviously upregulated in glioblastoma tissues compared with adjacent normal tissues." (PMID 31612863, 2019). "The cAMP responsive element binding protein 3 (CREB3) pathway is a major contributor to the malignant progression of glioblastoma." (PMID 31612863, 2019). "Then, qRT-PCR and Western blotting were used to detect CREB3 levels in glioblastoma tissues and cell lines, respectively." (PMID 31612863, 2019). "We also investigated the effects of overexpressing or knocking down CREB3 in glioblastoma cells to explore a new therapeutic strategy for this disease." (PMID 31612863, 2019). "In glioblastoma cells, the overexpression of CREB3 increased proliferation and invasion, while the downregulation of CREB3 induced apoptosis and inhibited invasion." (PMID 31612863, 2019). "To determine the function of CREB3 in glioblastoma, we overexpressed CREB3 in SHG-44 cells." (PMID 31612863, 2019). "In conclusion, we demonstrated that CREB3 was upregulated in patients with glioblastoma." (PMID 31612863, 2019). "We next explored whether the inhibition of CREB3 induced apoptosis in glioblastoma cells by regulating the ERS pathway." (PMID 31612863, 2019). "One of these DEGs was CREB3, which is known to promote the malignant progression of glioblastoma." (PMID 31612863, 2019). "CREB3 was upregulated in glioblastoma tissues and cell lines." (PMID 31612863, 2019). "Since glioblastoma is an aggressive type of brain tumor, we investigated whether overexpressing or downregulating CREB3 would alter the invasive abilities of glioblastoma cells." (PMID 31612863, 2019). "Our findings indicate that CREB3 functions as a tumor promoter in glioblastoma, and thus could serve as a treatment target in glioblastoma patients." (PMID 31612863, 2019). "However, the complete mechanism by which knocking down CREB3 induces apoptosis in glioblastoma requires further investigation." (PMID 31612863, 2019). "To assess the effects of CREB3 in glioblastoma, we employed a human astrocyte cell line (HA1800) and three glioblastoma cell lines (SHG-44, U251MG and U87MG)." (PMID 31612863, 2019). "Next, qRT-PCR and Western blotting were used to detect the expression of CREB3 in human astrocytes (HA1800 cells) and three glioblastoma cell lines (SHG-44, U251MG and U87MG)." (PMID 31612863, 2019). "Thus, CREB3 may function as a tumor promoter in glioblastoma patients." (PMID 31612863, 2019). "CREBRF acts as a tumor suppressor of glioblastoma through the suppression of ATG5 and CREB3." (PMID 36358691, 2022).
prostate carcinoma (6 papers, 2019 to 2024). A carcinoma that arises from epithelial cells of the prostate gland. "In androgen‐dependent prostate cancer, CREB3 interacted with AR, and suppressed its transcriptional activity, leading to decreased proliferation of prostate cancer cells." (PMID 38952575, 2024). "In prostate cancer, CREB3 played an opposite role in different cancer subtypes." (PMID 38952575, 2024). "In addition, CREB3 is reported to be involved in the malignant phenotype of prostate cancer via the androgen receptor." (PMID 30940151, 2019). "Furthermore, CREB3 plays a significant role in cervical cancer progression via the c-Jun-mmp9 axis and is involved in the malignant phenotype of prostate cancer." (PMID 30940151, 2019).
glioma (4 papers, 2016 to 2024). A benign or malignant brain and spinal cord tumor that arises from glial cells (astrocytes, oligodendrocytes, ependymal cells). "CREB3 regulatory factor (CREBRF), a negative regulator of CREB3 (cAMP responsive element binding protein 3), contributes an important part in hypoxia-induced autophagy in glioma cells." (PMID 36071472, 2022).
viral infection (4 papers, 2013 to 2022). "Another link between CREB3 and viral infection in the CNS is provided by the CREB3-Herp (homocysteine-induced ER protein) pathway in the Poliovirus (PV)-induced apoptosis." (PMID 31334233, 2019). "Based on the strong correlative aspects between HPSE and CREB3 during HSV-1 infection, we hypothesized that HPSE and CREB3 overexpression might correspondingly upregulate each other during viral infection." (PMID 35746643, 2022). "Additionally, HPSE expression remained unchanged with CREB3 overexpression; however, it significantly increased with viral infection." (PMID 35746643, 2022). "Second, HCFC1 is known to interact with CREB3, a protein previously shown to be involved in leukocyte migration._ENREF_37 This study further shows that the protein may have a role in cell migration regulation in processes other than virus infection." (PMID 23593504, 2013).
cervical cancer (3 papers, 2017 to 2024). A primary or metastatic malignant neoplasm involving the cervix. "Previous studies have indicated that CREB3 can bind directly to the c-Jun promoter and subsequently enhance mmp9 activity in cervical cancer cells, which contributes to cervical cancer progression." (PMID 30940151, 2019).
brain tumor (2 papers, 2019 to 2021). "Moreover, it has been documented to block autophagy through the CREB3/ATG5 pathway in brain tumor." (PMID 34276768, 2021).
diabetes (2 papers, 2019 to 2024). "In the hippocampus, expression of GR and Creb3, a modulator of GR sensitivity, were consistently reduced in C5aR1 knockout mice, suggesting an overall genotype-specific alteration in sensitivity to glucocorticoids, a phenotype also observed in patients with diabetes." (PMID 38628385, 2024). "And finally, the signaling circuit TNF signaling pathway:CREB3, which neither presents a different activity in the comparison nor the functions triggered are likely to be directly related with diabetes." (PMID 31831811, 2019).
hepatocellular carcinoma (2 papers, 2023 to 2024). A malignant tumor that arises from hepatocytes. "cAMP responsive element binding protein 3 (CREB3), belonging to bZIP family, was reported to play multiple roles in various cancers, but its role in hepatocellular carcinoma (HCC) is still unclear." (PMID 38952575, 2024). "cAMP responsive element binding protein 3 (CREB3) hinders the progression of hepatocellular carcinoma (HCC) by suppressing the phosphorylation of AKT signaling through binding competitively with insulin receptor substrate 1 (IRS1) to insulin receptor (INSR)." (PMID 38952575, 2024).
lung adenocarcinoma (2 papers, 2023 to 2024). A carcinoma that arises from the lung and is characterized by the presence of malignant glandular epithelial cells. "Conversely, in lung cancer, the depletion of CREB3 protein levels have shown to impede tumour progression and induce apoptosis in lung adenocarcinoma cells." (PMID 38894657, 2024). "SEC61G participates in endoplasmic reticulum stress by interacting with CREB3 to promote the malignant progression of lung adenocarcinoma." (PMID 37491302, 2023).
melanoma (2 papers, 2023 to 2024). A malignant, usually aggressive tumor composed of atypical, neoplastic melanocytes. "To examine the role of CREB3 in cancer cell proliferation, we introduced CREB3-FL and CREB3-CF into SK-MEL-2 melanoma cells." (PMID 38480902, 2024). "The heatmap was used to demonstrate the expression levels of the genes TBX21, ZNF799, HEY2, ZNF580, IRF4, CREB3, and ZNF93 during the pseudotime trajectories of four distinct subtypes of melanoma cells." (PMID 37435067, 2023).